SP1 (Sp1 transcription factor)
Diseases named in the same sentence as SP1 in open-access papers (continued):
Sharing a sentence is not in itself a finding about the gene and the disease.
multiple myeloma (continued). "ChIP-qPCR analysis confirmed that in the absence of HDACi, c-Myc is present on the CD26 promoter of myeloma cells via binding to Sp1 located on the proximal G-C box, thereby repressing the promoter and leading to reduced CD26 transcription in myeloma cells." (PMID 38284882, 2024). "In contrast, in the presence of HDACi, c-Myc was shown to be dissociated from Sp1 and its binding was replaced by acetylated c-Myc on K323 on the CD26 promoter of myeloma cells, leading to activation of the promoter and initiation of CD26 transcription." (PMID 38284882, 2024). "In multiple myeloma, NEAT1 forms a positive feedback loop with SP1, in which NEAT1 induces SP1 expression by sequestering hsa-miR-29b-3p, and SP1 targets NEAT1 promoter region inducing NEAT1 transcription, and collectively promoting tumor cell survival." (PMID 35008626, 2021). "Addition of MTM results in decreased IL-6 production and myeloma cell growth, whereas the ERK inhibitor U0126 strongly inhibits SP1 recruitment at the IL-6 promoter site." (PMID 23667526, 2013). "In addition to the induction of oxidative stress, this compound was reported to downregulate the expression of IRF-4, Sp-1, and the IKZF-1-IRF4-MYC axis, key factors for myeloma cell growth and survival, in MM cells." (PMID 38510655, 2024). "In contrast, in the presence of HDACi, c-Myc is detached from the CD26 promoter via Sp1 with the increased acetylation of c-MycK323 and the promoter is thereby activated, leading to initiation of CD26 transcription as well as activation of cytotoxicity in several myeloma cells." (PMID 38284882, 2024). "More specifically, MALAT1, expressed at high levels in the MSCs from myeloma patients, was shown to recruit the transcription factor SP1 on the LTBP3 promoter contributing to the increase of LTBP3 expression, most likely by stabilizing the interaction between SP1 and SP1-consensus sequences." (PMID 27177333, 2016).
Obesity (22 papers, 2013 to 2026). Accumulation of substantial excess body fat. "Finally, we noticed that the important metabolic regulator PGC-1α, through its interaction with SP1, was involved in regulating the SP1–LanCL1 axis to cope with hypothalamic oxidative stress caused by obesity." (PMID 38397850, 2024). "We hypothesized that decreased SLC2A4 gene expression in the VAT of obese humans with impaired glycemic control (high HbA1c) emerges from a fatty-acid-induced (dietary or obesity-associated) increase in DNA methylation in a SLC2A4 enhancer region spanning several SP1 and SREBPF-1 binding motifs." (PMID 37047391, 2023). "Here, we showed that knockdown of Lgr4 in nestin progenitor or Sp1 mature neurons reduced high fat diet (HFD)-induced obesity by increasing energy expenditure and inhibiting food intake." (PMID 40069508, 2025). "Our findings show the critical importance of the hypothalamic PGC-1α-SP1-LanCL1 axis in regulating HFD-induced obesity, and provide new insights describing the correlations of hypothalamic inflammation and oxidative stress during this process." (PMID 38397850, 2024). "All these results provided evidence showing PGC-1α was involved in the response of LanCL1 to HFD exposure, and suggested an important role of the PGC-1α–SP1–LanCL1 axis in protecting against HFD-induced obesity." (PMID 38397850, 2024). "Protecting against miR-181c oxidation by inhibiting Sp1 offers potential therapeutic targets for obesity or type 2 diabetes cardiomyopathy." (PMID 39252788, 2024). "Ubiquitous overexpression of SP1 in brain neurons results in hyperphagia and obesity in both mice and Drosophila." (PMID 26569394, 2015). "Our previous studies demonstrate that hyperphagia in SP1 mice results in obesity since SP1 mice are pair-fed with the same amount of food as WT mice for 10 weeks, which can totally prevent the SP1-induced obesity." (PMID 26569394, 2015). "SP1 not only is located within ±1 Mb of obesity SNP rs1443512 (similar to ITGA5), but also has the highest differential expression percentage (63.6%)." (PMID 24455749, 2013). "Eight genes (BCAT1, BMP2 K, CSRNP2, MYNN, NCKAP5L, SAP30BP, SLC35B4, and SP1) were isolated as candidates for obesity." (PMID 24455749, 2013). "Also, our work demonstrates that the PGC-1α-coordinated activity of the SP1–LanCL1 axis couples HFD exposure with obesity development/progress." (PMID 38397850, 2024). "Interestingly, Sp1 protein expression in mice with diet-induced obesity was much higher in white adipose tissue than in the liver." (PMID 34073755, 2021). "The prediction analysis showed that FTOBD‐associated variants disturb binding sites of SP1 and SP2; obesity‐associated variants, on the other hand, disturb binding sites of FOXP1, which are transcription factors highly expressed during prenatal development stages of the brain." (PMID 31033179, 2019). "Furthermore, we demonstrated that Sp1 contributes to the obesity-induced FGF21 upregulation in mouse adipose tissue and hepatic FGF21 upregulation in hepatocarcinogenesis." (PMID 28466020, 2017). "Furthermore, we identified Sp1 contributes to the obesity-induced FGF21 upregulation in mouse adipose tissue and hepatic FGF21 upregulation in hepatocarcinogenesis." (PMID 28466020, 2017). "These suggest that Sp1 may be responsible for the elevated FGF21 expression in adipose tissue of diet-induced obesity mice." (PMID 28466020, 2017). "Given that Sp1 positively regulates FGF21 basal transcriptional activity in HepG2 cells and 3T3-L1 cells, we investigated whether Sp1 has a direct effect on the upregulation of FGF21 transcription in HFD-induced obesity mice model." (PMID 28466020, 2017). "The Sp1‐mediated inhibition of DsbA‐L gene expression may be responsible for obesity‐induced adiponectin downregulation and insulin resistance." (PMID 26763486, 2016).
Obesity (continued). "In individuals with obesity, circulating exosomal miR-4449 showed increased expression compared to the healthy control group, and its expression decreased after bariatric surgery, while miR-199a-3p regulates liver fat production by targeting SP1, suggesting a treatment for MASLD." (PMID 40668532, 2025). "Therefore, it is interesting but unknown whether a sexual dimorphic effect is present in the hypothalamic PGC-1α–SP1–LanCL1 axis in regulating the development and progress of obesity." (PMID 38397850, 2024). "Additionally, emerging evidence suggests that both SP1 and STAT3 can suppress the expression of pivotal genes implicated in adipocyte differentiation, including PPARγ, C/EBPα, and FABP4, thereby potentially restoring insulin sensitivity and mitigating obesity." (PMID 37445596, 2023). "Our findings provided direct evidence showing the implications of the PGC-1α–SP1–LanCL1 axis in the development and progress of HFD-induced obesity." (PMID 38397850, 2024). "Our results suggest that Sp1 regulates liver and adipose tissue FGF21 expression in normal physiological states and contributes to the obesity-induced FGF21 upregulation in adipose tissue and hepatic FGF21 upregulation in hepatocarcinogenesis." (PMID 28466020, 2017). "Using the same method, seven highly ranked genes (BAP1, GRB14, HSP90AB1, ITGA5, NCKAP5L, SP1, and TOMM5) within ±1 Mb of obesity SNPs were identified." (PMID 24455749, 2013). "In summary, the activation of EP3 receptor inhibits HFD-induced obesity in mice by promoting macrophage releasing SPARC via the PKA/Sp1/Dnmt1,3a pathway, indicating that the EP3 receptor may be an attractive therapeutic target for obesity." (PMID 40702315, 2025). "SP1 mRNA level was also significantly downregulated in adipose tissue of overweight and obese humans, which was consistent with the downregulation of AKAP1 in obesity." (PMID 33747723, 2021). "In SP1 mice, a decrease in the efficacy of CCK to reduce meal size and c-Fos expression in hind brains at least partly contributed to SP1-induced hyperphagia and obesity." (PMID 26569394, 2015). "Interestingly, we found that Sp1/C/EBPβ cross-talk inhibited the increase of RANTES expression in response to SP, which may imply a link between obesity and regulation of atherogenic RANTES expression via C/EBPβ." (PMID 29998198, 2018). "Thus, our results demonstrate that Sp1 positively regulates the basal transcription of FGF21 in the liver and adipose tissue and contributes to the obesity-induced FGF21 upregulation in mouse adipose tissue and hepatic FGF21 upregulation in hepatocarcinogenesis." (PMID 28466020, 2017).
cardiac hypertrophy (21 papers, 2012 to 2026). "Neuroplastin is upregulated under ER stress and can induce inflammation via NF-kB activation, while trans-acting transcription factor 1 (also known as Sp1) is associated with MI and cardiac hypertrophy." (PMID 40332511, 2025). "Specifically, reduced levels of Sp1 O-GlcNAcylation are associated with physiological cardiac hypertrophy, which typically regresses with decreased exercise intensity." (PMID 39252788, 2024). "SYNE1 has been shown also to be involved in angiotensin-II-induced cardiac hypertrophy by the miR-525-5p/specific protein transcription factor SP1 axis." (PMID 40076866, 2025). "Conversely, elevated Sp1 O-GlcNAcylation levels exacerbate mitochondrial dysfunction and contribute to pathological cardiac hypertrophy and myocardial fibrosis in patients with diabetic cardiomyopathy." (PMID 39252788, 2024). "In recent years, several studies have highlighted the significant role of SP1 in cardiomyocyte growth and cardiac hypertrophy." (PMID 39062521, 2024). "In this case, the modification of Cys664 abolished the Krüppel-like factor 5 (KLF5) promoter binding to SP-1 and inhibited cardiac hypertrophy (because when SP-1 is coupled with KLF5 promoter, it has a pro-hypertrophic effect in the heart)." (PMID 38247849, 2024). "Sp1 regulates physiological processes such as angiogenesis, inflammation, lipid metabolism, endothelial dysfunction, pathological cardiac hypertrophy, hypertension, and aortic aneurysm." (PMID 39252788, 2024). "Sp1 overexpression and knockdown experiments showed that Sp1 acted as an important mediator in the regulation of cardiac hypertrophy." (PMID 34462460, 2021). "Our results indicate that protocatechuic acid acts via the ROCK1/Sp1/PKCγ axis and therefore has promising therapeutic potential as a treatment for cardiac hypertrophy." (PMID 34462460, 2021). "This is the first report demonstrating that Sp1 directly contributes to cardiac hypertrophy as determined by the measurement of cell size." (PMID 34462460, 2021). "Cardiac hypertrophy markers, such as Nppa, Nppb, and Myh7, were also upregulated by Sp1 overexpression." (PMID 34462460, 2021). "Sp1 can potentially promote cardiac hypertrophy by activating the transcription of a panel of hypertrophic genes, including troponin T, ANF, HCN2/4, and SERCA2." (PMID 33015041, 2020). "In conclusion, gentisic acid effectively inhibited cardiac hypertrophy and fibrosis in a mouse model of pressure overload through downregulation of Sp1/GATA4 expression and ERK1/2 signalling pathways." (PMID 30256522, 2018). "Our results showed that gentisic acid treatment did indeed attenuate cardiac hypertrophy and fibrosis, through down‐regulation of Sp1/GATA4 and MAPK signalling." (PMID 30256522, 2018). "Cardiac hypertrophy‐associated upregulation of the transcription factors GATA4 and Sp1 and activation of extracellular signal‐regulated kinase 1/2 were also negated by these drugs." (PMID 30256522, 2018). "Moreover, SP1 contributes to cardiac hypertrophy through the activation of gene transcription, impacting diseases like pathological cardiac hypertrophy and HCM differently due to distinct pathogenesis." (PMID 39062521, 2024). "Cumulatively, these studies suggest that targeting SP1 could be a promising approach to managing pathological cardiac hypertrophy and HCM." (PMID 39062521, 2024). "Furthermore, knockdown of SP1 was reported to restrain Ang-II-induced cardiac hypertrophy by regulating the ceRNA network of SNHG14/miR-322-5p/miR-384-5p/PCDH17." (PMID 35048778, 2022). "The transcription factors GATA4, GATA6 and SP1 are reported to induce cardiac hypertrophy." (PMID 35719043, 2022). "To decipher the role of Sp1 in cardiac hypertrophy, we transfected H9c2 cells with pCMV-Sp1." (PMID 34462460, 2021). "Our data indicate that ROCK1, Sp1, and PKCγ are involved in the development of cardiac hypertrophy and, therefore, could be used as new therapeutic targets for cardiac hypertrophy." (PMID 34462460, 2021).
cardiac hypertrophy (continued). "In addition, Sp1, in cooperation with nuclear receptors, appears to be essential for the metabolic reprogramming during cardiac hypertrophy by orchestrating the transcription of fatty acid oxidation-related genes." (PMID 33015041, 2020). "On the other hand, few reports have revealed the usefulness of specific Sp1 inhibitor(s) in the treatment of cardiac hypertrophy partly because Sp1 is a universally present molecule and partly because sequence-specific transcription factors are notorious to drug." (PMID 33015041, 2020). "In the current investigation, we decided to determine whether gentisic acid from this extract affects the Sp1/GATA4 pathway in pressure overload‐induced cardiac hypertrophy." (PMID 30256522, 2018). "Additionally, S-sulfhydration of Sp1 prevents cardiac hypertrophy by regulating angiotensin." (PMID 39252788, 2024). "In particular, we demonstrated that the SP1 inhibitor plicamycin and the EGR1 inhibitor ML264 had therapeutic effects on attenuating cardiac hypertrophy in an HCM mouse model, possibly by reversing fetal reprogramming." (PMID 38780967, 2024). "H2S reduces the promoter activity of Krüppel-like factor 5 (KLF5) and the expression of mRNA, and the S-sulfhydration of SP-1 by H2S at Cys664 weaken the activity of SP-1 and KLF5 promoter binding and inhibits cardiac hypertrophy." (PMID 37492730, 2023). "Research indicates that SP1-induced SNHG14 aggravates cardiac hypertrophy by sponging miR-322-5p and miR-384-5p to upregulate protocadherin 17 (PCDH17), making SNHG14 a potential biomarker for cardiac hypertrophy." (PMID 41602333, 2026). "Indeed, we found that the inhibition of SP1 and EGR1, which are newly found TFs with fetal chromatin accessibility patterns in patients, markedly repressed cardiac hypertrophy in HCM mice and thus provided potential drug targets for HCM treatment." (PMID 38780967, 2024). "Furthermore, upregulation of SP1 was also observed in recent studies, where it interacted with KLF5, lncRNA CTBP1-AS2, SYHE1-AS1, PCDH17, SNHG14, and PED5 promoter regions to influence cardiac hypertrophy development." (PMID 39062521, 2024).
Huntington disease (21 papers, 2007 to 2025). Huntington disease (HD) is a rare neurodegenerative disorder of the central nervous system characterized by unwanted choreatic movements, behavioral and psychiatric disturbances and dementia. "This explains that SP1 is associated with the pathophysiology of some neurodegenerative and neuroinflammatory disorders, including Alzheimer’s and Huntington’s disease and multiple sclerosis." (PMID 34831151, 2021). "The predicted Sp1 site in the Vdac1 gene was of special interest since aberrant Sp1 mediated interaction has earlier been implicated in Huntington's disease mechanism." (PMID 18000542, 2007). "SP1 is a protein-coding gene that is linked with Huntington's disease and embryonal carcinoma." (PMID 35003319, 2021). "In Huntington’s disease, pathogenic SP1 cascades cause repression of neuronal genes." (PMID 34831151, 2021). "However, the preferential interaction of Sp1 with mutant huntingtin interferes with the functions of Sp1 and TAF4, resulting in the inhibition of binding of Sp1 to DNA, which is associated with the pathogenesis of Huntington's disease." (PMID 23326574, 2013). "Studies have indicated that Sp1 is upregulated in models of Huntington’s disease (HD), and reducing its levels offers neuroprotective benefits." (PMID 40425782, 2025). "Up regulation of SP1 is shown to be tumorigenic and its reduction was found to be neuroprotective in in vitro and in vivo models of Huntington’s disease." (PMID 26919708, 2016). "Finally, Bax, Hdac2 and Sp1, involved in apoptosis and transcription, are found among the Huntington’s disease-specific genes affected by LPS and LPS + IFNγ." (PMID 30382133, 2018). "Huntington’s disease, a neurodegenerative disease, is caused by mutated Huntington protein that interacts with Sp1 and thus fails to bind to DNA43." (PMID 28717181, 2017). "In Huntington's disease (HD), mutant huntingtin (mHtt) disrupts the normal transcriptional program of disease neurons by altering the function of several gene expression regulators such as Sp1." (PMID 21179468, 2010). "Indeed, in Huntington's Disease (HD) it was previously reported that Sp1 levels were robustly increased in caudate postmortem tissues but decreased in the hippocampus." (PMID 17786189, 2007). "Similarly, decreased expression of the Huntington’s disease-related genes Sp1, Hdac2 and Bax, as a result of both treatments could provide some clues about the underlying disease mechanisms." (PMID 30382133, 2018). "The pathways related to neurodegenerative disease, such as Alzheimer’s disease and Huntington’s disease, were also enriched with two essential DEPs (GAPDH, PLCB3 and SP1, PLCB3, respectively)." (PMID 35741576, 2022). "It is interesting to mention that in another neurodegenerative disorder, such as Huntington disease, it has been demonstrated that in NG108 cells overexpressing mutant Huntingtin (mHtt) Sp1 up-regulates REST by binding its promoter sequence." (PMID 34899171, 2021).
non-small cell lung carcinoma (20 papers, 2007 to 2025). A group of at least three distinct histological types of lung cancer, including non-small cell squamous cell carcinoma, adenocarcinoma, and large cell carcinoma. "Cholesterol induces resistance to epidermal growth factor receptor tyrosine kinase inhibitors (EGFR-TKIs) in non-small cell lung cancer (NSCLC) via the EGFR/Src/Erk/SP1 signaling pathway 31, while elevated levels in lipid rafts induce gefitinib resistance." (PMID 38617549, 2024). "ΔNp63α and SP1-mediated monocarboxylate transporter 4 has been observed to be correlated with the aerobic glycolysis-preference subtype of non-small cell lung cancer." (PMID 35590288, 2022). "Other researchers have proved that SP1 regulates the progression of non-small-cell lung cancer by recruiting OTUB1." (PMID 33537306, 2020). "Its translocation is regulated by heat shock cognate 70 to exert angiogenic functions and controls c-Jun/Sp1-dependent transcriptional activation of cPLA2alpha in phorbol ester-treated non-small cell lung cancer A549 cells." (PMID 27602772, 2016). "LncRNA LINC01234-induced by SP1 as a ceRNA promotes non-small cell lung cancer by modulating OTUB1." (PMID 31737900, 2020). "HSPB1/HSP27 may also activate NCL through SP1, as NCL has been reported to physically interact with SP1 in non-small cell lung cancer, and human epidermal keratinocytes." (PMID 26108672, 2015). "In non-small cell lung cancer, lncRNA MIR31HG could sponge miR-241 to upregulate SP1, thus stimulating tumor progression." (PMID 35936736, 2022).